COMT (catechol-O-methyltransferase)
Diseases named in the same sentence as COMT in open-access papers (continued):
Sharing a sentence is not in itself a finding about the gene and the disease.
Anxiety (continued). "COMT gene, for example, codes for a catecholamine catabolic breakdown enzyme, which is known to be involved in anxiety development as high levels of COMT have been observed in patient's serum." (PMID 27563374, 2016). "COMT degrades catecholamines such as dopamine, epinephrine, and norepinephrine, and has been shown to influence anxiety and personality." (PMID 25722948, 2015). "For example, genetic variants of catechol-O-methyltransferase (COMT) have been associated with a tradeoff between cognitive ability and behavioral measures of anxiety and stress resilience, giving rise to the so-called Worrier/Warrior selectionist model." (PMID 24860472, 2014). "Neuropsychiatric symptoms in persons with 22q11.2 deletion, including obsessive compulsiveness, anxiety, hyperactivity, and one prior case report of TS, have been attributed to low copy number effects on Catechol-O-Methyltransferase (COMT)." (PMID 20069037, 2009). "Additionally, we analysed the interactions between the COMT genotypes, personality traits and anxiety measures." (PMID 38540358, 2024). "Therefore, in the presented study we analysed personality dimensions measured by the NEO-Five Factor Inventory, and anxiety measured by the State-Trait Anxiety Inventory together with COMT rs4680." (PMID 38540358, 2024). "Although anxiety may be affected by occupational experience and environmental factors, the results showed that 5-HTTLPR and COMT play a crucial role in affecting dancers’ anxiety and mood in the presence of pain." (PMID 39590895, 2024). "Moreover, some significant genes within these nominally significant overlapping pathways have been previously associated with pain problems and/or anxiety symptoms (e.g., the ZNRD1 gene; the MDK gene; the FOXO3 gene; the COMT gene; the NFATC4 gene)." (PMID 37146008, 2023). "Pain perception as well as anxiety were compared according to COMT genotypes." (PMID 37834942, 2023). "In addition, the moderating effect of COMT Val158Met on the relationship between antenatal maternal anxiety and neonatal cortical thickness showed a similar pattern." (PMID 38666110, 2023). "The influence of the COMT polymorphisms (p.158Val/Met, c.472G/A) on inhaled nitrous oxide analgesia during labour and delivery, as well as anxiety as a personality trait, have not been evaluated according to our knowledge." (PMID 37834942, 2023). "Furthermore, in a combined analysis of two large cohorts (ALSPAC and PREDO) there was a robust interaction effect of child COMT (val/val rs4680) genotype with maternal prenatal anxiety to predict ADHD symptoms assessed at multiple time points." (PMID 34413728, 2021). "Indeed, in a combined analysis of two large cohorts (ALSPAC and PREDO), prenatal anxiety and child COMT genotype predicted ADHD symptoms at multiple time points." (PMID 34413728, 2021). "Self‐reported pain during fixed orthodontic treatment was not influenced by sex, age, time into treatment, anxiety, nor by polymorphisms of COMT, HTR2A or NR3C1 genes." (PMID 34273191, 2021). "COMT adds methyl groups to the neurotransmitters, preventing their ability to bind to their respective receptors, thereby limiting neural response to emotional stimuli, such as fear and anxiety." (PMID 33528889, 2021). "Prior research has demonstrated that there is a relationship between between the COMT rs4680 and the impact of COVID-19, which could plausibly be mediated by maladaptive anxiety-related behaviour." (PMID 34682575, 2021). "Interestingly, in rats with experimentally induced low COMT activity, propranolol had a marked reduction in pain sensation and the affective component of pain as manifested by pain anxiety-related behaviors." (PMID 33276542, 2020). "Several studies have examined the link between gene variants of catechol‐O‐methyltransferase (COMT), an enzyme important for metabolizing the neurotransmitter dopamine in certain brain areas (e.g., PFC), and anxiety‐related traits or disorders in men and women." (PMID 31631413, 2020).
Anxiety (continued). "The current state of knowledge does not allow generalizations regarding the involvement of the COMT Val158Met polymorphism in anxiety, role of the alleles involved, interactions with other genes and hormones, or interactions with sex and age." (PMID 31156495, 2019). "This incidental finding could influence the severity of symptoms observed in this case, and it is also possible that supplementation for low COMT could alleviate some of the anxiety Patient 1 is experiencing." (PMID 31111659, 2019). "Variants mapping the COMT gene (rs4680, rs6269, and rs4818) correlated with Anxiety of new onset, but not when defined as a chronic variable." (PMID 30656852, 2019). "Additionally, associations with Catechol-O-methyltransferase (COMT) Val158Met polymorphism were examined, motivated by prior associations of this single nucleotide polymorphism (SNP) with stress (or “anxiety”) related personality traits." (PMID 29623060, 2018). "Our findings implicating COMT for regulating the prenatal maternal anxiety prediction of executive function and inattention/hyperactivity are of interest for identifying a potential mechanism for work on prenatal anxiety and for expanding COMT-focused research on developing neurocognitive functions." (PMID 28614354, 2017). "COMT mouse studies also offer support for a link between low COMT activity and greater anxiety." (PMID 27388330, 2016). "Increased anxiety in female catechol-O-methyltransferase (COMT) knockout animals with increased cortisol levels and a role for COMT in modulating stress-related hormonal and immune parameters in a manner that depends on chronicity of the stressor has been demonstrated." (PMID 24690771, 2014). "The current fear-potentiated startle study, based on previous studies of COMT genotype and fear, anxiety, and trauma, initially explored the relationship between the COMT Val158Met polymorphism and conditioned fear responses in an inner-city population of traumatized individuals." (PMID 23596403, 2013). "Another study suggests that individuals with slowing alleles in the COMT rs4680-AA and COMT rs4633-TT as observed in our negatively affected cases (HDA-AU) may experience increased sensitivity to anxiety and stimuli, potentially explaining such effects." (PMID 39148948, 2024). "For example, the Val158Met polymorphism of catechol-O-methyltransferase (COMT, which is related to dopamine catabolism in the PFC and is regulated by estrogen) contributes to the complex Sex × Gene × Environment interactions affecting dopamine-dependent neurocognition and anxiety [e.g., 323, 324]." (PMID 38087196, 2023). "Whether COMT polymorphism affects pregnant women's labor anxiety and analgesia has not been reported." (PMID 35346044, 2022). "From this literature, it is not possible to formulate more specific hypotheses on the COMT Val158Met polymorphism effects on anxiety-related manifestations that could eventually be applied to MA." (PMID 31156495, 2019). "It, therefore, seems either directly or indirectly because of low enzyme activity or through cofactor deficits that MAO inhibition, COMT inhibition, and inhibited histamine metabolism may together contribute to anxiety, fear, and over-arousal in our patient sample." (PMID 27148083, 2016). "Variables that may mediate this association include variants of the catechol-O-methyltransferase gene, anxiety, and negative beliefs about the self or others." (PMID 26345291, 2015). "The dopamine/norepinephrine system, as crucially driven by the COMT Val158Met polymorphism, ought not to be considered in an isolated way with respect to the modulation of anxiety or related phenotypes, but rather in interaction with other relevant neurotransmitter systems." (PMID 22745815, 2012). "However, there are also reports indicating no influence of COMT Val158Met on anxiety disorders or related phenotypes or demonstrating association of the less active met allele with anxiety-related phenotypes." (PMID 22745815, 2012).
Anxiety (continued). "Additionally, recent research suggests that measuring catechol-o-methyltransferase levels may serve as an indicator of preoperative anxiety, as anxious individuals tend to exhibit lower levels of this enzyme and higher levels of circulating catecholamines during the preoperative period." (PMID 38138172, 2023). "For instance, functional brain imaging revealed an additive effect of COMT Met158 and 5-HTTLPR S alleles on the response of the amygdale, hippocampal and limbic cortical areas to unpleasant stimuli, suggesting that persons with those alleles may show a lowered resilience against an anxiety mood." (PMID 30991630, 2019). "Interestingly, there is also a report of a slight association between the COMT met158 allele and teacher rated anxiety in autistic students which nicely fits to our finding of an increased amygdala activation in CD38 risk allele carriers also carrying the COMT met158 allele." (PMID 23554586, 2013). "Also, neurotransmitter-related genetic markers, including the catechol-O-methyltransferase (COMT) and serotonin transporter (SLC6A4) genes, have been studied as potential targets for individualized anxiety treatment." (PMID 41590228, 2025). "Moreover, the spatial distributions of MAOA, MAOB, COMT, and SLC6A4 on the left side of the network suggested that these genes significantly contributed to the pathogenesis of anxiety." (PMID 38684743, 2024). "On the other hand, it is not yet clear if COMT moderation of prenatal maternal anxiety represents a robust effect, on other child outcomes." (PMID 28614354, 2017). "The data presented here suggest that modest alterations in COMT activity do not alter gross changes in anxiety-like behaviors, at least in the tests used here." (PMID 27388330, 2016). "Furthermore, especially before a competition, where dancers experience increased stress, the trait anxiety score of the Y-Elite dancers was higher than that of the Pro dancers for each genotype group by the Kruskal–Wallis test (5-HTTLPR: p < 0.027; COMT: p < 0.019)." (PMID 39590895, 2024). "In our study, pain and anxiety affected the outcome, but were not connected to the COMT haplotypes." (PMID 29195501, 2017). "Maternal prenatal anxiety was based on self-report measures; child symptoms of ADHD were collected from 4–15 years of age; working memory was assessed from in-person testing at age 8 years; and genetic variation in COMT at rs4680 was determined in both mothers and children." (PMID 28614354, 2017). "We observed no increase in anxiety-related behaviors in the COMT-Met mice." (PMID 27388330, 2016). "However, some of the earlier findings are sex specific and not all COMT transgenic mice showed anxiety changes." (PMID 27388330, 2016). "Indeed, even where there were numerical differences between groups (none of which were close to statistical significance), COMT-Met mice demonstrated numerically lower levels of anxiety-like behaviors compared with wild-type mice." (PMID 27388330, 2016). "Homozygous deletion on COMT (catechol-O-methyltransferase), one of the major mammalian enzymes involved in the metabolic degradation, impairment in emotional reactivity in the dark/ light exploratory model of anxiety were displayed in female, but not in male mice." (PMID 33171840, 2020). "However, they do not preclude the possibility that COMT may influence anxiety phenotypes under specific genetic or environmental conditions." (PMID 27388330, 2016). "Genotypes of COMT val158met or 5-HTTLPR with high functionality (val/val or l/*) determined greater cardiovascular effects, and with low functionality (met/* or s/s) negative subjective effects (dizziness, anxiety, sedation)." (PMID 23112822, 2012).
psychosis (81 papers, 2005 to 2026). "COMT Val carriers showed significantly increased psychosis risk following adolescent cannabis use compared to Met/Met homozygotes (OR = 10.9 for Val/Val carriers using cannabis by age 15 vs. OR = 1.1 for Met/Met carriers)." (PMID 41561992, 2025). "In the context of environmental interactions, cigarette smoking is associated with hypermethylation of the MB-COMT promoter, while cannabis use interacts with the COMT Val158Met genotype/epigenotype to influence psychosis risk." (PMID 41234420, 2025). "Decreased dopamine catabolism related to the COMT gene polymorphism increases psychosis proneness in individuals with a history of traumatic life events." (PMID 38645418, 2024). "Among the genes modulating dopamine transmission, the COMT gene harbors the Val158Met polymorphism (rs4680), which influences brain morphology and functional connectivity in psychosis." (PMID 36833277, 2023). "The COMT rs4680 variant appears to modulate the association between cannabis use and psychotic disorders, particularly in individuals who were exposed to cannabis at an early age." (PMID 37509416, 2023). "An increased risk of psychosis was also seen in adults who used cannabis in their teen years and possessed a specific variant of the catechol-O-methyltransferase (COMT) gene, which codes for an enzyme involved in dopamine and norepinephrine degradation." (PMID 36949890, 2023). "COMT is one of the most important genes associated with behavioral properties and psychotic disorders." (PMID 34492034, 2021). "A longitudinal study following individuals to adulthood looked into a specific polymorphism (Val158Met) in COMT, as a potential gene moderator for the association between cannabis use and psychosis development." (PMID 34946799, 2021). "The results of the study implicated the COMT Val158Met Val allele as a link between adolescent cannabis use and an increased risk for later psychosis." (PMID 34946799, 2021). "Several studies have shown the COMT Val158Met genotype to be a moderator of the relationship between cannabis use and the later development of a psychotic disorder, with the highest risk for Val carriers." (PMID 32059350, 2020). "As was also concluded by a recent meta-analysis, an association between the COMT Val158Met genotype, cannabis use, and psychosis cannot be proven at the moment, accounting for the dissimilarity in results." (PMID 32059350, 2020). "For example, the catechol-O-methyltransferase (COMT) Val158Met genotype, involved in dopamine turnover in the prefrontal cortex, was shown to interact with the impact of cannabis use on psychosis risk." (PMID 32059350, 2020). "When studying single candidate genes, AKT1 and COMT have frequently been associated with cannabis use and an increased risk of psychosis." (PMID 32059350, 2020). "Regarding the COMT gene, several studies have shown the Val158Met genotype to be a moderator of the association between cannabis use and the later development of a psychotic disorder, with the highest risk for Val carriers." (PMID 32059350, 2020). "The influence of COMT genotype and the interaction with sex on GM volume appears to be more prominent in populations who are at risk for psychosis relative to healthy volunteers (McIntosh, Baig, & Hall, 2007; Ohnishi, Hashimoto, & Mori, 2005)." (PMID 32772512, 2020). "Another study revealed an increased risk of psychosis among adults who carry a specific variant of the gene for catechol-O-methyltransferase (COMT) enzyme and used cannabis during adolescence." (PMID 31920665, 2019). "DAOA gene (13q34) and COMT gene (22q11) are not only associated with psychotic disorders, but also play a key role in glutamatergic and dopaminergic neurotransmissions (Ross, Margolis, Reading, Pletnikov, & Coyle, 2006)." (PMID 30719257, 2018).
psychosis (continued). "Polymorphisms in the catechol-O-methyltransferase gene (COMT)—an enzyme involved in dopamine metabolism and some forms of psychosis —are linked with cannabis dependence, as well as THC-induced impairments in working memory and executive functions." (PMID 28680405, 2017). "While COMT haplo-insufficiency has been proposed as one explanation for the increased risk of psychosis in 22q11DS, it should be noted that, overall, the association between COMT genotype and psychosis remains inconclusive." (PMID 27429661, 2016). "COMT haplo-insufficiency in 22q11DS has been suggested as one explanation for the increased susceptibility for psychosis in 22q11DS." (PMID 27429661, 2016). "The first reported specific gene–environment interaction for a psychotic disorder included a functional polymorphism in the catechol-O-methyltransferase (COMT) gene." (PMID 24860514, 2014). "A cross-sectional analysis of 918 individuals in Europe found a significant three-way interaction between the COMT Val allele, cannabis use, and childhood abuse in moderating psychosis." (PMID 24904437, 2014). "For instance, a study of hyperprolinemia in 22q11DS showed an association between hyperprolinemia and psychosis in 22q11DS patients only when Met, the low activity allele of the COMT gene, was taken into account." (PMID 21738766, 2011). "In the third study they reported that a functional variant of the catechol-O-methyltransferase gene (COMT Val158Met) would moderate the risk of cannabis use by adolescents on the later development of psychosis in adult life." (PMID 16887023, 2006). "In the literature, COMT impacts MC response, psychosis risk, and cognitive impairment." (PMID 40407530, 2025). "Recent studies suggest a relationship between PRODH and COMT, where hyperprolinemia may exacerbate dopaminergic dysfunction, increasing the risk of psychosis, particularly in individuals with low COMT activity." (PMID 40362210, 2025). "The significant impact of the COMT Val158Met polymorphism on processing speed, particularly in patients with schizophreniform disorder, offers a compelling insight into the cognitive differences between early and advanced stages of psychotic disorders." (PMID 39518545, 2024). "Similarly, also polymorphisms in the catechol-O-methyltransferase (COMT) gene seems to moderate the psychosis-inducing effect of cannabinoids, thus strengthening the theory that dopamine moderation can influence psychosis and psychotic-like behaviors." (PMID 35002789, 2021). "They followed adult-onset cannabis users with psychosis and controls, and showed that individuals homozygous for the Val allele at COMT Val158Met were more sensitive to the effects of delta-9-tetrahydrocannabinol (THC), the main psychotropic component in cannabis, on cognition and psychosis." (PMID 34946799, 2021). "This could be the result of haplo-insufficiency of COMT in these patients, and may play a role in their increased risk for developing cognitive impairments and psychotic disorders." (PMID 30935427, 2020). "Individuals with the Val/Val genotype have been reported to have higher levels of thyroxylase mRNA in mesencephalic dopamine neuronal populations that project to the striatum, which may explain why the COMT valine allele leads to susceptibility to psychosis." (PMID 28707072, 2018). "Interestingly, in one study, the effects of the interaction between the COMT Val158Met polymorphism and cannabis use on age at onset of schizophrenia spectrum disorders and non-psychotic disorders were tested." (PMID 28822116, 2018). "One example of gene-cannabis interaction is the hypothesized moderating effect of the catechol-O-methyl transferase (COMT) polymorphism Val158Met (COMTVal158Met) in the association between cannabis use and the emergence of the psychosis phenotype." (PMID 29444152, 2018).